IL6 (interleukin 6)
Diseases named in the same sentence as IL6 in open-access papers (continued):
Sharing a sentence is not in itself a finding about the gene and the disease.
tumor (continued). "Afterwards, the expression levels of 12 cytokines including IL-1a, IL-1b, IL-2, IL-4, IL-6, IL-8, IL-10, IL-12, IL-17A, TNFα, IFNγ and GM-CSF in secretome of hWJ-MSCs alone as well as in supernatant of tumor cells before and after treatment with hWJ-MSCs secretome were evaluated." (PMID 31857970, 2019). "CRP is released by the liver upon IL-6 signaling that in turn promotes tumor progression." (PMID 31788452, 2019). "Here, we have revealed a TRAPs-mediated regulatory mechanism of CD4+ T cells differentiation whereby HSP90α on the surface of TRAPs educate CD4+ T cells via a TLR2–autocrine IL-6 cascade to express IL-10 and IL-21 and engender immune suppression to promote tumor growth and metastasis." (PMID 31300052, 2019). "Two of the well-studied cytokines produced by tumor cells are Interleukin 6 (IL-6) and IL-8." (PMID 31075939, 2019). "This may be due to the stimulation of IL-6 secretion in the tumor microenvironment, which in turn affects immune tolerance." (PMID 31417646, 2019). "Furthermore, selective activation of ERß has an anti-carcinogenic effect on tumor microenvironment via the downregulation of inflammatory signaling (interleukin-6)." (PMID 31818262, 2019). "One study designed HA-based combination adjuvant systems by combining HA with immunostimulatory compounds (HA; Mw = 500–1300 kDa), showing anti-tumor therapeutic effects by prevention of tumor proliferation and a significant increase in the cytokine secretion of IL-6 and TNF-α." (PMID 31266194, 2019). "Of interest, that it has been previously found that IL-6 is necessary for calreticulin mediated priming of Th17 cells and inhibiting the generation of Treg cells and Th17 cells play an important role in establishing of anti-tumor immunity." (PMID 31842994, 2019). "IL-6 protein expression in tumor samples was investigated by immunohistochemistry." (PMID 31766212, 2019). "In tumor xenografts, injection with resveratrol markedly reduced IL-6 level." (PMID 30791624, 2019). "Increased IL-6 concentration in plasma can be considered as early and sensitive, although nonspecific, indicators of various inflammations, which in this case should be identified with the destruction of tumor tissue." (PMID 31861531, 2019). "Upregulated expression of IL-6 in malignant melanoma cells increased osteoclastogenesis, which could induce the proliferation of tumour cells." (PMID 31334678, 2019). "In tumor cells, IL-6 can drive EMT, therapy resistance, and invasive characteristics." (PMID 31684144, 2019). "This is due to the pro-tumor effects of IL-6 in tumor cells and stromal components." (PMID 31684144, 2019). "Interleukin 6 (IL-6) is a proinflammatory cytokine released by cells in the tumor microenvironment." (PMID 31572184, 2019). "IL-6 is produced by a broad variety of cells, including immune cell and tumor cells." (PMID 31192215, 2019). "Plasma IL-4, IL-6 and TNFα levels were significantly increased in tumor-bearing versus normal mice." (PMID 31752313, 2019). "Finally, we performed an IHC array to analyse IL-6/IL-8 (interleukin 6/interleukin 8) expression in 103 pairs of tumours and matched adjacent tissues of patients with ESCC to elucidate the correlation between IL-6 or IL-8 and clinical characteristics." (PMID 31324197, 2019). "Studies describing this cell non-autonomous pro-tumorigenic function include epithelial-mesenchymal transition and invasion, tumor vascularization, immune surveillance, and abnormal tissue morphology, mediated by proinflammatory cytokines IL-6 and IL-8, metalloprotease MMP3 and VEGF among others." (PMID 31137607, 2019). "However, addition of exogenous IL6 to tumor cell culture can restore STAT3 signal transduction and increase VEGF expression." (PMID 31355138, 2019). "Ex vivo experiments with tumor associated macrophages showed that SW could partially modulate macrophage phenotype, decreasing CCL2 secretion and impairing IL-10 and IL-6 upregulation, which prompted us to proceed to in vivo tests." (PMID 30840689, 2019).
tumor (continued). "The pivotal role of IL-6, secreted from HSCs or the tumor environment, may entail direct enhancement of HCC growth rather than induction of MDSCs." (PMID 31614930, 2019). "IL-6 levels were markedly higher in tumor tissues than in benign tissues." (PMID 30755239, 2019). "IL-6 mRNA levels were significantly increased in tumor tissue." (PMID 31694340, 2019). "The role of IL-6 in the tumor pathogenesis seems to be more complex." (PMID 31342143, 2019). "More importantly, Cyr61 may paly regulation action in the upstream for tumor inflammatory microenvironment formation and maintain, especially for IL-6 expression." (PMID 31766991, 2019). "However, the IL-6 mRNA level is significantly higher in adjacent normal tissue than in tumor tissue, and single gene analysis of IL-6 in survival probability of LUAD patients is not significant (data not shown)." (PMID 31443242, 2019). "Increased IL-6 secretion is likely due to the growing tumors in tumor-bearing mice." (PMID 31878338, 2019). "In the lungs, alveolar and interstitial macrophages upon taking up these EVs start to secret CCL2 favoring the recruitment of iMo, which in turn differentiate into macrophages, mostly M2-like cells, promoting tumor growth by the secretion of IL-6 and deposition of fibrin." (PMID 31447834, 2019). "Furthermore, we found that S1PR1–STAT3 upregulation in tumor cells induces IL-6, which activated S1PR1–STAT3 in MDSCs in the liver, leading to premetastatic niche formation prior to CRC cell arrival." (PMID 31534132, 2019). "Nevertheless, as a small molecule IL-6 gene transcription inhibitor, the effect of apigenin on IL-6 is likely to be more tissue and tumor type specific and therefore may have less toxic side effects." (PMID 31572184, 2019). "In cancer cachexia animal models, elevated IL-6 has been shown to promote glucocorticoid-mediated immune suppression, which results in limited T-cell chemotaxis and poor response to immune checkpoint inhibition in the tumor microenvironment." (PMID 31683709, 2019). "In addition, IL-6 has been correlated with tumor stage and cancer stem cell (CSC)-like properties in human HCC." (PMID 31771617, 2019). "IL-6 is produced by the tumor and also by pleural mesothelial cells and stromal cells." (PMID 30999958, 2019). "The secretion of IL-6, a negative regulator of NK function, tended to increase in the tumor rather than in the adjacent tissue as its concentration reached 135.7 ± 50 pg/ml in the tumor compared to 34.9 ± 11 pg/ml in the adjacent healthy tissue." (PMID 31105699, 2019). "Regarding tumor characteristics, detectable IL-6 was significantly associated with large tumor size (>5 cm, P = 0.001), multiple rather than solitary tumors (P = 0.008), and the presence of PVT (P < 0.001)." (PMID 30824840, 2019). "This implies an intrinsic aggressiveness-inducing ability of IRISOE TNBC tumor cells, which through secreting a high level of IL-6 (and possibly others), recruit and activate MSCs to enhance their own aggressiveness by reciprocally exacerbating EP2 and EP4 activation on tumor cells through PGE2." (PMID 31014367, 2019). "It is known that malignant epithelial cells secrete antiadipogenic cytokines, such as TNF-α, IL-11, and IL-6 that inhibit the differentiation of fibroblasts near the tumor into mature adipocytes and stimulate aromatase expression in these undifferentiated adipose fibroblasts." (PMID 31412584, 2019). "Interestingly, blocking IL-6 trans-signaling had a similar effect as deletion of the IL-6 gene since sgp130Fc transgenic mice also showed strongly reduced tumor numbers." (PMID 31694340, 2019). "IL-6 also downregulates specific microRNAs resulting in increased transcription of DNMT1 (an enzyme used to methylate cytosine to alter gene expression) resulting in decreased expression of tumour suppressor genes (see ‘microRNA changes’ below)." (PMID 30819129, 2019).
tumor (continued). "Similarly, genetic variants of the genes encoding elements of IL-6/JAK/STAT3 pathway were related to the risk, course, prognosis and response to treatment of different neoplasia, but available data concerning BCC are scarce." (PMID 31342143, 2019). "Therefore, IL-17C-mediated expression of tumor-promoting cytokines (e.g. IL-6) seems to decrease the sensitivity to PD-1 blockade." (PMID 31316109, 2019). "Moreover, embelin has been observed to suppress tumor growth through interleukin 6/STAT3 signaling in various cancer types, and can also inhibit tumor metastasis." (PMID 31635287, 2019). "Additionally, activated PSCs promote tumor progression by secreting IL-6, TGF-β, stromal cell-derived factor-1 (SDF-1), hepatocyte growth factor (HGF), and galectin-1 (Gal-1, 38]." (PMID 30987642, 2019). "Secretion of IL-6 by tumor cells and tumor microenvironment cells contributes to STAT3 activation." (PMID 31695609, 2019). "However, since resistance to selumetinib in these tumour xenografts was also reported to be unstable, its relation to IL‐6 levels is uncertain." (PMID 30582770, 2019). "Interleukin 6 plays critical roles in the differentiation and expansion of tumor cells." (PMID 31572184, 2019). "Moreover, this study showed that elevation of serum inflammatory cytokines (TNFα and IL-6) in tumor-bearing mice are in sync with and dependent on the elevation of serum Hsp70 and Hsp90." (PMID 31480237, 2019). "Large platelets could release a variety of pro-inflammatory cytokines such as interleukin-6 (IL-6), which may improve tumor progression and metastasis." (PMID 30612568, 2019). "The IL6/STAT3 signaling pathway has been extensively explored in tumor progression." (PMID 31486564, 2019). "In non-treated Kras mice, tumor-associated neutrophils and tumor-promoting cytokines (e.g. IL-6 in BAL fluids) were almost not detectable." (PMID 31316109, 2019). "In addition, because IL-6 signaling cannot only promote anti-tumor-adaptive immunity, but also drive malignancy, the role of IL-6 in this NFs-based vaccine system should be examined further in vivo." (PMID 31382455, 2019). "So we considered that IL-6 may elicit pro-tumor effect on both gefitinib-sensitive and gefitinib-resistant NSCLC cell lines." (PMID 31523190, 2019). "Notably, TRAPs-elicited CD4+ T cells inhibited CD4+ and CD8+ effector T cell function in an IL-6- and IL-10-dependent manner and induced IL-10-producing regulatory B cells (Bregs) via IL-6, IL-10 and IL-21, thereby promoting tumor growth and metastasis." (PMID 31300052, 2019). "IFNγ, IL-1β, tumor TNFα, TGFβ, IL-6, and IL-18 are key to the functionality of TAM." (PMID 31430935, 2019). "Therefore, an examination of the efficacy of IL-6 therapy in WM patients is necessary to evaluate its effect on IgM levels and tumor growth." (PMID 31164961, 2019). "However, IL-6 from different sources, such as tumor cells, fibroblasts, and immune cells, is known to promote tumor growth, invasion, and anti-apoptotic potential in cancer cells." (PMID 30927911, 2019). "We elected to evaluate in detail the role of IL-6 in IRISOE TNBC tumor aggressiveness." (PMID 31014367, 2019). "Several papers have reported that IL-6 inhibits the immune response to tumour cells." (PMID 31324197, 2019). "However, here we arrived at this finding through the unbiased screening of 41 cytokines/chemokines, whereas in our previous work, IL-6 and IL-8 were preselected for their study in the tumor microenvironment." (PMID 31769424, 2019). "To investigate whether CAFs also upregulate IL-6 expression in an in vivo xenograft model, we performed the immunohistochemistry of IL-6 using the tumor tissues from mice treated with 5-FU." (PMID 30927911, 2019). "Likewise, STAT3 activation induces IL-6 gene transcription and, thus, establishes a feedback loop in tumor tissues." (PMID 31695609, 2019).
tumor (continued). "The activation of the IL-6/STAT-3 signaling axis apparently is an important event in cancer because it promotes carcinogenesis by regulating multiple survival signaling pathways in tumor cells." (PMID 31602271, 2019). "IL-6 inhibition decreased macrophage-mediated inflammation and increased apoptosis, suggesting the possibility that IL-6 controls disease progression through modulation of the microenvironment and/or direct effect on tumor cells." (PMID 31817625, 2019). "In their publication, the authors suggested a mechanism by which CCL2 and IL-6 potentiate tumor progression, as the tumor infiltrating monocytes are protected from apoptosis (see CCL2 Enhances Myeloid Cell Survival and Proliferation) and skewed toward a protumorigenic M2 phenotype." (PMID 31921102, 2019). "Indeed, tumorigenesis was strongly reduced to the same extent in IL-6−/− mice and sgp130Fc transgenic mice indicating that IL-6 trans-signaling strongly contributed to tumor formation in the APCmin/+ model." (PMID 31694340, 2019). "At the same time, the correlation of Cyr61 with IL-6, other inflammatory markers and clinicopathologic features was analyzed respectively to explore the potential association of Cyr61with EOC progression in the tumor-associated inflammatory response." (PMID 31766991, 2019). "Notably, our earlier study has indicated that IL-6 is among the cytokines showing the highest increase in CRC, as well as the strongest association with high tumor stage." (PMID 31196200, 2019). "To further analyse whether CAR-147 macrophage reinfusion causes cytokine storms like CAR-T cell infusion does, we detected the cytokines IL-1β, IL-6, IL-12, TNFα, and IFNγ in serum samples and tumour homogenates." (PMID 31570753, 2019). "Mice with K-ras mutant lung tumors treated with anti-IL-6 antibodies have shown an overall reduction in tumor burden and a shift to a TME with a less proliferative and a less protumor inflammatory context: fewer Th17 cells, fewer Tregs, and more M1-type polarization." (PMID 32039025, 2019). "In this study, we demonstrated that IL-6 blockade reverses the effect of CAFs on tumor progression." (PMID 30744595, 2019). "Immature MDSCs are generated from BM cells and then they expand and migrate to the TME where a complex milieu of tumor- or stromal-derived factors including vascular endothelial growth factor, IL-6, IL-1β, GM-CSF, transforming growth factor β as well as PGE2 modulate their suppressive function." (PMID 31920649, 2019). "However, a different set of experiments demonstrated that recognition of melanoma cell lysates potently activated the IRE1/XBP1s axis in MoDCs, which increased the production of IL-6 and TNF and promoted cross-presentation of tumor-associated Ags in vitro." (PMID 31817075, 2019). "An anti-IL-6 therapy decreases PD-L1 expression and tumor size in a CD8+ T-cell-dependent manner." (PMID 31480382, 2019). "Upon secretion cytokine analysis, adipocyte-derived IL-6 or tumor-derived PAI-1 might exert roles in activating PLOD2 in CAAs." (PMID 31170987, 2019). "In addition, the effect of STAT3 inhibition on tumor cell proliferation was monitored by BrdU incorporation after IL6 stimulation." (PMID 31438567, 2019). "A general mechanism for this phenomenon could be that cytokines produced within the tumor induce the release of G-CSF, IL-1, and IL-6." (PMID 30944838, 2019). "IL-6 expression, on the other hand, was increased approximately 20-fold in the cortical and trabecular bone of tumor-bearing mice injected with MDA-MB-231GFP/Luc2 cells alone when compared to mice injected with MDA-MB-231GFP/Luc2 cells plus either EO-231 or MC3T3-E1 cells." (PMID 30813947, 2019).
tumor (continued). "Furthermore, CRC EVs also promote immunosuppressive activity by autocrine stimulation of the IL-6/STAT3 pathway leading to immune suppression via secretion of MDSC population thus facilitating tumor growth." (PMID 31146452, 2019). "This paradoxical finding may be attributed to the complex contextual nature of the tumor whereby many producers of IL-6 are various elements within the TME, particularly stromal and immune cells, such as macrophages, monocytes and inflammatory T cells." (PMID 31443242, 2019). "Interestingly, there is also recent evidence that the serum levels of the cytokines IL-6 and IL-8 can be used as biomarkers to predict not only the tumor response, but also the overall survival after TACE." (PMID 31683891, 2019). "To study if hMSCs could release cytokines in vivo, we measured the expression of TNF-α and IL-6 in tumor tissues by real-time PCR." (PMID 31142737, 2019). "In addition, a plethora of factors that are abundant in infiltrated cells that infiltrate the tumor microenvironment (TANs in particular) such as IL-6, IL-8, IL-1β, and TNFα are also able to induce EMT in GC." (PMID 30616627, 2019). "We performed multiplex immuno-assay (Luminex) to assess the presence of inflammatory cytokines involved in the regulation NK cells function, such as TNF-α, IFN-γ, IL-6, IL-15, and IL-1β, in the tumor microenvironment (black bars) and in the healthy adjacent tissue microenvironment (white bars)." (PMID 31105699, 2019). "Herein, we demonstrated for the first time that macrophages play an essential role in the potent pro-tumor effect of GC-MSCs; in turn, GC-MSCs induce the polarization of macrophages into the M2 subtype through secreting IL-6 and IL-8 via the JAK2/STAT3 signaling pathway." (PMID 31801938, 2019). "The idea of targeting IL-6 in cancer treatment is also relevant since a systemic inflammatory response is associated with a poorer outcome, independent of tumor stage." (PMID 30038723, 2018). "IL-17 induces IL-6 production by tumor-infiltrating immune cells and tumor cells and activates the signal transducer and activator of transcription 3 (Stat3)-dependent pathway that subsequently enhances tumor cell growth." (PMID 29515773, 2018). "Likewise, via the activation of G-protein-coupled receptors, LPA acts directly on tumour cells by stimulating the secretion of pro-osteoclastic interleukins such as interleukins (IL) IL-6 and IL-8 among others." (PMID 29300334, 2018). "Additionally, IL-6 is produced by CAFs and promotes tumor-cell migration and invasion, angiogenesis, and chemoresistance in various types of malignancies." (PMID 29444110, 2018). "In addition, the serum IL-6 level was dramatically elevated in saline-treated CT-26 tumor-bearing mice." (PMID 29662645, 2018). "Catecholamines derived from stress may induce increased levels of vascular endothelial growth factor (VEGF) and interleukin-6 (IL-6) on the tumor microenvironment, molecules which can drive angiogenesis and tumor growth." (PMID 30125310, 2018). "In 4T1 tumours grown in Il6−/− mice, there was a modest increase in the proportion of TAMs." (PMID 30054470, 2018). "Hence, the cut-off level of IL-6 as a tumor biomarker must be sufficiently high in order to only diagnose the patients with malignancies and not patient with inflammatory conditions, and still relatively low in order to detect all patients with malignancies." (PMID 30038723, 2018). "Serum IL-6 and IL-8 levels positively correlated with GC tumor size and tumor stage." (PMID 29988030, 2018). "Additionally, depletion of IL-6 has been shown to yield reductions in tumor burden and metastasis in experimental models." (PMID 30154439, 2018). "Furthermore, it has been reported that blockade of IL-6 affects tumor-infiltrating immune subsets, for example, reducing the number of myeloid-derived suppressor cells and their suppressive abilities." (PMID 29867925, 2018).